EGFR (epidermal growth factor receptor)
Diseases named in the same sentence as EGFR in open-access papers (continued):
Sharing a sentence is not in itself a finding about the gene and the disease.
lung cancer (continued). "A synergistic effect in the cells treated with As2O3 plus erlotinib or osimertinib (AZD9291) was detected in EGFR mutant lung cancer cells." (PMID 33042262, 2020). "Although epidermal growth factor receptor-tyrosine kinase inhibitors (EGFR-TKIs) are very effective against EGFR-mutant lung cancer, resistance to these drugs occurs within approximately 1 year, on average." (PMID 32552717, 2020). "The targeting of specific non-coding RNAs related to EGFR expression can serve as therapy options in order to inhibit prominent cell signaling pathways present in lung cancer." (PMID 32316322, 2020). "Epidermal growth factor receptor (EGFR) is frequently overexpressed and mutated in non-small cell lung cancer (NSCLC), which is the major type of lung cancer." (PMID 32093124, 2020). "To examine the anti-NSCLC activity of DPBA in vivo, we established the tumour xenografts models of A549, H1650, and H1975 cells, and a xenograft derived from a patient with primary EGFR-positive lung cancer." (PMID 33033232, 2020). "This likely relates in part to delays in diagnosis and higher frequencies of driver mutations (e.g., EGFR and ALK mutations in lung cancer patients)." (PMID 33218178, 2020). "For instance, EGFR, ALK, and ROS1 tyrosine kinase inhibitors against tumors with EGFR mutations, ALK fusions, and ROS1 fusions respectively, are already in use as standard treatments in lung cancer in clinical settings." (PMID 33264103, 2020). "Signal transduction crosstalk between AR and EGFR often leads to p38MAPK-dependent activation of mTOR and cyclinD1 expression in prostate cancer cells and in lung cancer cells." (PMID 32929340, 2020). "In contrast, FUT4 overexpression in lung cancer cells has been reported to suppress the EGFR signaling pathway and attenuate EGFR-mediated invasion of tumor cells." (PMID 32486143, 2020). "Despite being low frequency mutations, given the high prevalence of lung cancer overall, it is estimated that over 30,000 NSCLC patient new diagnoses per year will harbour rare EGFR mutations." (PMID 31562956, 2020). "These inhibitors include, among others, SNX-5422 for chronic lymphocytic leukemia (combined with ibrutinib, phase 1) and AT13387 for EGFR-mutant lung cancer (combined with erlotinib hydrochloride, phase 1–2)." (PMID 32397330, 2020). "Among them, TNF had the greatest degree in the HCT-major hub genes-disease network, while IL-6, JUN, EGFR, and MYC were shown to associate with the survival of lung cancer patients." (PMID 32595734, 2020). "To date, no report has described the correlation between SCARNA7 and NONHSAT017369 and lung cancer or EGFR signaling." (PMID 31691525, 2020). "This concept complements the current understanding of how a hyperactive kinase can contribute to EGFR mutant lung cancers 8-10." (PMID 32194831, 2020). "Targeting of anti-EGFR Nb in Nb@IC-NPs to lung cancer promote the accumulation of IR1048MZ, resulting in precise and sufficient tumor oxygen production to retard tumor hypoxia and enhance PDT of lung cancer." (PMID 33292202, 2020). "The average capture efficiency of EGFR, Vimentin and FA magnetic spheres used alone and in combination to lung cancer cell lines was 78%, 79%, 82% and 91%, respectively." (PMID 32336066, 2020). "Recent studies have demonstrated that EVs successfully isolated from BALF of lung cancer patients contain an abundant amount of dsDNA, and that liquid biopsy for EGFR genotyping using BALF is tissue-specific and extremely sensitive compared to cfDNA analysis." (PMID 33575258, 2020). "Actually, the immunotherapy based on antibodies against the Programmed Death-ligand 1 (PD-L1) and epidermal growth factor receptor (EGFR) tyrosine kinase inhibitors are some targeted therapies in lung cancer." (PMID 32294884, 2020). "Here, we tried to untangle the controversies surrounding Mig-6 function as a protagonist or an antagonist of EGFR-TKI resistant lung cancer." (PMID 32552717, 2020).
lung cancer (continued). "In this study, by retrospectively analyzing the largest known genetic dataset of lung cancer patients, we uncovered a total of 85 different EGFR e20ins and observed disparate responses to EGFR inhibitors in a subset of patients." (PMID 32412152, 2020). "The resistance of lung cancer to epidermal growth factor receptor-tyrosine kinase inhibitor (EGFR-TKI) is one of the unconquered frontiers in chemotherapy." (PMID 32552717, 2020). "Our study identified that E19 dels were a predictor for good prognosis in EGFR positive lung cancer, similar to previous results; conversely, an E21 mutation significantly increased mortality." (PMID 32053675, 2020). "We next sought to explore our findings in the context of mutant EGFR lung cancers, which possess an immunosuppressive microenvironment but present with low levels of PD-L1 compared to KRAS mutant lung cancers." (PMID 32908154, 2020). "The EGFR gene overexpression has also been correlated to several other types of cancer, including anal and lung cancers." (PMID 32104177, 2020). "CTCs were captured from the peripheral blood of 30 patients with lung cancer using EG‐P‐LMB, and the captured CTCs were analyzed for EGFR gene mutation." (PMID 32856417, 2020). "The EGFR T790M-L858R mutant was initially found in human lung cancer patients with EGFR-TKI resistance." (PMID 33092268, 2020). "Recent studies have revealed that pyroptosis of cancer cells can be induced by molecular targeted agents specifically targeting K-Ras-, epidermal growth factor receptor (EGFR)- or anaplastic lymphoma kinase-driven lung cancer." (PMID 33665167, 2020). "The impact of the VS-6063/JQ1 combination on cell viability appeared equal to that of VS-6063 with Cisplatin, an anti-NSCLC chemotherapeutic agent for treating lung cancer or Osimertinib, a third generation of EGFR inhibitor." (PMID 32793596, 2020). "Taken together, these data indicated that EGFR-TKIs mediate lung cancer cell VEGFC expression, which further regulates lymphatic vessel formation." (PMID 31892990, 2020). "Although parthenolide suppressed in vivo tumor growth of lung cancer by targeting NF-κB target and inducing ROS, the basic oncogenic role of EGFR in NSCLC and its specific pharmacological of parthenolide in NSCLC is little known." (PMID 33292235, 2020). "SAH-JGZ4 reduced the tumor-initiating cell (TIC) frequency by sixfold (1/TIC from ~93 cells to ~546 cells), suggesting that targeting EGFR stability is a potential strategy to inhibit the stemness of lung cancer cells." (PMID 32694521, 2020). "In our cohort, the EGFR positive group had a higher prevalence of stage IV lung cancer, but a significantly better prognosis, which was probably related to higher rates of TKI treatment." (PMID 32053675, 2020). "A novel predicted transcription regulation between a TF TFAP2C and an oncogene EGFR was experimentally verified in lung cancer cells." (PMID 33054712, 2020). "They identified DTPs while testing the acute response of EGFR mutant nonsmall cell lung cancer cells (NSCLCs) to a lethal EGFR inhibition." (PMID 33213500, 2020). "CCK8 assay showed that NAC plus gefitinib combination overcame EGFR‐TKI resistance in non‐small cell lung cancer (NSCLC) cells by lowering the value of half maximal inhibitory concentration (IC50)." (PMID 31891230, 2020). "Downregulation of Ezrin in lung cancer cells has resulted in actin cytoskeleton rearrangements, reduced EGFR activity and phosphorylation levels of downstream signaling pathways, as well as a substantial reduction in cell migration and invasion." (PMID 33240887, 2020). "Resistance to epidermal growth factor receptor-tyrosine kinase inhibitors (EGFR-TKIs) has become the main clinical challenge of advanced lung cancer." (PMID 33262410, 2020).
lung cancer (continued). "A Phase 1/1b clinical trial of AURKA inhibitor Alisertib with osimertinib in metastatic EGFR-mutant lung cancer is currently recruiting participants (NCT04085315)." (PMID 32292420, 2020). "The EGFR impact score indicated robust predictive power for the prognosis of early-stage lung cancer because this score can evaluate the impact of the EGFR pathway on the tumor and genomic instability." (PMID 32277151, 2020). "It has been reported that transcriptional activation of cyclin D1 via HER2/HER3 contributed to EGFR‐TKI resistance in lung cancer cells." (PMID 32898333, 2020). "We experimentally verified a novel predicted regulation, i.e., the regulation of TF TFAP2C on a hot once-gene EGFR, in lung cancer cell A549 and conceived a potential three TFBSs molecular mechanism." (PMID 33054712, 2020). "This study suggests that the combination of EGFR-TKIs and FGFR-TKIs is effective for lung cancer cells, thus providing conceptual support for the expansion of the existing EGFR-TKIs." (PMID 33092268, 2020). "Among the two meta-analysis that have been conducted to determine the effect of EGFR expression on survival outcomes in lung cancer, results have been variable." (PMID 33247670, 2020). "Herein, we utilize long-read sequencing to reconstruct the sequence of the individual haplotypes present within the EGFR landscape of two different lung cancer patients." (PMID 31940362, 2020). "In head and neck as well as lung cancer cells, EGFR mediates HIV+ exosome entry into target cells and participates in exosome-induced cellular signaling, including ERK1/2 phosphorylation, without activating the receptor." (PMID 32051269, 2020). "A number of studies have shown that targeting EGFR can inhibit lung cancer growth including antibodies, small molecule inhibitors, oligonucleotides, peptidomimetics and others." (PMID 33292235, 2020). "Considering that EGFR is one of hottest onco-genes in lung cancer, we looked into the predicted TFs for EGFR by dlGRN on the three lung cancer data sets." (PMID 33054712, 2020). "Liquid biopsy has emerged as a minimally invasive alternative to tumor tissue analysis for the management of lung cancer patients, especially for epidermal growth factor receptor (EGFR) oncogene addicted tumor." (PMID 36046387, 2020). "In lung cancer, tumour-derived EVs carrying EGFR decreased the IFN-β response in monocytes and macrophages and stimulated a dendritic cell-mediated immunosuppressive tumour microenvironment." (PMID 33143170, 2020). "Overactivation of EGFR is an important driver in the development of lung cancer due to activation of a series of downstream events that trigger multiple signaling pathways." (PMID 33193885, 2020). "EGFR-mutant lung cancers will inevitably develop resistance after treatment with earlier-generation EGFR TKI." (PMID 32067121, 2020). "Approximately one percent of EGFR-mutant lung cancer patients develop resistance to EGFR targeting therapeutics that is accompanied by a phenotypic switch from ADC to SCC." (PMID 32292420, 2020). "On the basis of results from a large study, these clinico-pathologic features of EGFR seem to be consistent in patients with lung cancer BMs67." (PMID 32483122, 2020). "In conclusion, using EGFR-TKI alone for brain metastasis in EGFR-mutant lung cancer patients showed outcomes comparable to those using upfront RT followed by EGFR-TKI." (PMID 32298306, 2020). "We previously identified that YAP, transducer of the Hippo pathway, is increased in metastatic tumor cells, and elevation of YAP/TAZ participates in EGFR-TKI sensitivity in lung cancer cells." (PMID 33375719, 2020). "The several previous studies focused on the simultaneous occurrence of EGFR mutations and ALK rearrangements in a unifocal lung cancer." (PMID 32375829, 2020).
lung cancer (continued). "Our data provided novel and further molecular rationale and preclinical data to support the combination of metformin with EGFR TKIs to treat EGFR-mutant lung cancer patients, especially with acquired resistance." (PMID 33014814, 2020). "Metformin also abolished gefitinib- and osimertinib-induced p65 phosphorylation, further demonstrating metformin suppressed NF-κB activity in EGFR-mutant lung cancer." (PMID 33014814, 2020). "LCD inhibited lung cancer cell proliferation through ATP competitive inhibition of EGFR and MET as a single drug." (PMID 32070026, 2020). "The identification of epidermal growth factor receptor (EGFR) as a driver oncogene has dramatically effected lung cancer treatment strategy." (PMID 31183631, 2020). "In patients with nonsmall cell lung cancer, CBX3 expression has a significant correlation with EGFR mutations." (PMID 33273987, 2020). "Among the >38,000 cases sequenced at Foundation One, EGFR KDD was detected in 5 out of approximately 7200 lung cancers (0.07%), 3 gliomas, 1 soft tissue sarcoma, 1 peritoneal serous carcinoma and 1 Wilms’ tumor." (PMID 32490123, 2020). "Our study sheds new light onto the mechanisms of osimertinib resistance and provides a rationale for targeting CDK4/6 as a potential therapy in overcoming third‐generation EGFR‐TKIs in lung cancer treatment." (PMID 32677256, 2020). "Although these mutations and rearrangements of EGFR, ALK, and ROS1 occur in a higher number of lung cancer cases, several other kinases show rare mutations and a wide range of different fusion genes and associated partners." (PMID 35582610, 2020). "Meanwhile, ING5 knockdown promoted migration and invasion through up-regulating EGFR/PI3K/Akt signaling pathway in lung cancer cells." (PMID 32308564, 2020). "Among those tested, the most common tests administered during baseline were EGFR, molecular cytogenetics (FISH) for ALK or ROS-1, tumor immunochemistry panels (PD-1, PD-L1) and combination lung cancer panels (EGFR, KRAS, ALK, ROS-1, and PD-L1)." (PMID 32187231, 2020). "For the most frequently targeted genes in lung cancer, such as EGFR, a high concordance rate of more than 90% has been shown between alterations detected in liquid biopsy and matched tissue samples." (PMID 33207619, 2020). "To determine the relationship between TRIB3 and EGFR levels in lung cancer, we detected the expression of these two proteins in several human lung cancer cell lines." (PMID 32694521, 2020). "Both cannabinoid agonists inhibited the proliferation and expression of EGFR in lung cancer cells, and CBD potentiated the effect of THC." (PMID 32049991, 2020). "Osimertinib mesylate is a mutant epidermal growth factor receptor (EGFR) inhibitor that can penetrate the blood-brain barrier and inhibit tumor cell survival and proliferation in patients with non–small cell lung cancer (NSCLC) with specific EGFR alterations." (PMID 32211870, 2020). "More importantly, our data demonstrated that metformin significantly increased sensitivity of resistant lung cancers to EGFR TKIs and dramatically delayed acquired resistance emergence in vitro and in vivo." (PMID 33014814, 2020). "EGFR tyrosine kinase inhibitors (TKIs) were the first to trigger the molecular profiling of lung cancer, as they demonstrated high response rates in tumors with EGFR exon 19 and 21 drug-sensitizing mutations." (PMID 33102215, 2020). "Although EGFR targeted therapy recorded success, it functions in only ∼15% of patients with lung cancer." (PMID 33344441, 2020).
lung cancer (continued). "The development of resistance to EGFR blockade in the treatment of lung cancer has been investigated for over 10 years, making it one of the best-studied examples of therapeutic resistance." (PMID 32898185, 2020). "In contrast to the mutual exclusivity of many oncogenic drivers in lung cancers, PIK3CA mutations frequently coexist with other oncogenic driver mutations, especially EGFR and KRAS." (PMID 33363040, 2020). "EGFR is often overexpressed in many tumors, including lung cancer, breast cancer, colorectal cancer, and pancreatic tumors.[[qv: 12]] Notably, EGFR inhibitor has been approved for the clinical treatment of lung and pancreatic cancer." (PMID 32274304, 2020). "VEGFA and EGFR are common therapeutic targets for lung cancer and closely related to the survival and prognosis of lung cancer patients." (PMID 32148531, 2020). "Although concomitant EGFR mutations and ALK fusion in lung cancer had once been considered to be mutually exclusive, the coexistence of EGFR mutations and ALK fusion in patients with lung cancer has been detected in a series of studies in recent years." (PMID 33520689, 2020). "Although clinical evidence indicates that EGFR-mutant lung cancers rarely benefit from anti-PD-1/PD-L1 immunotherapy, recent studies, such as ATLANTIC and IMpower150, have reported more positive results for PD-1/PD-L1 inhibitors in EGFR-mutant lung cancers." (PMID 32944405, 2020). "The acquired resistance to EGFR-TKIs greatly hampers the success of targeted therapy against lung cancer." (PMID 32751169, 2020). "In various cancer types, miR-128 functions as a tumor suppressor, targeting epidermal growth factor receptor in lung cancer, polycomb complex protein BMI1 in prostate cancer, PAICS in bladder cancer, and E2F transcription family member E2F3a in glioblastoma." (PMID 32218208, 2020). "With the rapid development of management of lung cancer, molecular target therapy of tyrosine kinase inhibitors (TKI) has exerted survival benefit for the NSCLC patients with EGFR mutations." (PMID 32093621, 2020). "Two meta-analysis covering several clinical trials observed relatively poor efficacy and low response rates to PD-1/PD-L1 inhibitors vs. standard second-line chemotherapy among patients with pre-treated EGFR-mutant lung cancer." (PMID 32760402, 2020). "Over-expression of EGFR in lung cancer has been documented previously, although most studies used tissue specimens for EGFR testing." (PMID 33247670, 2020). "Many lung cancers (when mutated)-related genes were up-regulated by smoking in specific cell populations, including TP63 in BC and EGFR in intermediate cells." (PMID 32727470, 2020). "The authors also found that the (Z)-TMS inhibited the phosphorylation and activation of EGFR in gefitinib-resistance lung cancer cells, induced caspase-independent apoptosis, and autophagy, and causing endoplasmic reticulum (ER) stress and AMPK activation." (PMID 32726968, 2020). "Current guidelines recommend that all patients with adenocarcinomas be tested for routine biomarkers, including EGFR mutations, ALK rearrangement, and ROS1 rearrangement, because FDA-approved agents for lung cancer are available for these biomarkers." (PMID 33005033, 2020). "The epidermal growth factor receptor (EGFR), a known lung cancer driver, and the growth factor receptor-bound protein 2 (GRB2), an adaptor protein involved in many oncogenic signaling pathways appeared as main hubs in this network." (PMID 32575471, 2020). "It is well known that TKI treatment leads to a dramatically improved prognosis in patients with EGFR positive lung cancer." (PMID 32053675, 2020).